MRPL36 (mitochondrial ribosomal protein L36)
Synonyms: L36mt; MRP-L36; RPMJ; PRPL36; bL36m
Tractability: Small molecule: a structure with a bound ligand is known.
Gene: Protein-coding gene on chromosome 5 (1,798,381 to 1,802,001, reverse strand). Ensembl gene ENSG00000171421.
Subcellular location: Mitochondrion
Subcellular location (Human Protein Atlas): Mitochondria; Nuclear bodies
Pathways (Reactome):
Metabolism of proteins: Mitochondrial ribosome-associated quality control; Mitochondrial translation elongation; Mitochondrial translation initiation; Mitochondrial translation termination
Gene Ontology:
Molecular function: structural constituent of ribosome
Biological process: mitochondrial translation; translation
Cellular component: mitochondrial large ribosomal subunit; mitochondrion; mitochondrial inner membrane; ribosome
Genetic constraint (gnomAD): Loss-of-function variants: 2 observed, 3.74 expected, observed/expected ratio (o/e) 0.53, 90% interval 0.22 to 1.56. That is too few expected variants to judge how well the gene tolerates losing a copy. Missense variants: 148 observed, 138.67 expected, observed/expected ratio (o/e) 1.07, 90% interval 0.93 to 1.22. Synonymous variants: 68 observed, 54.94 expected, observed/expected ratio (o/e) 1.24, 90% interval 1.02 to 1.51.
Homologues: Orthologues: chimpanzee MRPL36 (100% identical), macaque MRPL36 (87% identical), mouse Mrpl36 (59% identical), dog MRPL36 (56% identical), pig MRPL36 (56% identical), rat Mrpl36 (56% identical), guinea pig MRPL36 (51% identical), tropical clawed frog MRPL36 (39% identical), Drosophila melanogaster mRpL36 (37% identical), zebrafish mrpl36 (36% identical), Caenorhabditis elegans mrpl-36 (25% identical).
Diseases named in the same sentence as MRPL36 in open-access papers:
MRPL36 is named in the same sentence as 5 diseases in open-access papers, as found by Europe PMC text mining. Sharing a sentence is not in itself a finding about the gene and the disease. The quoted sentences say what the papers report.
ovarian carcinoma (4 papers, 2021 to 2025). A malignant neoplasm originating from the surface ovarian epithelium. "MRPL36 is another example of a promising risk predictor, particularly in relation to breast and ovarian cancer metastasis." (PMID 39354291, 2024). "Kaplan-Meier survival analysis shows that high expression of MRPL15, MRPL36, MRPL39, and MRPS16 is significantly associated with poorer OS in ovarian cancer patients." (PMID 40371222, 2025). "(2021) revealed an apparent association between high MRPL36 expression and upregulation of HE4 in ovarian cancer." (PMID 39354291, 2024). "MRPL10, MRPL15, MRPL36, MRPL39, and MRPS16 were highly expressed in ovarian cancer, whereas MRPS31 showed the opposite tendency." (PMID 33934540, 2021). "The results showed that MRPL36 and MRPL15 had the highest genetic variation rate in ovarian cancer, with gene amplification as the most common type." (PMID 33934540, 2021). "Six MRPs (MRPL10, MRPL15, MRPL36, MRPL39, MRPS16, and MRPS31) related to HE4 in ovarian cancer were selected." (PMID 33934540, 2021). "Comparison of the relationship between these genes and the prognosis of ovarian cancer showed that overexpression of MRPL15, MRPL36, and MRPS31 may lead to poor OS and PFS in patients with ovarian cancer, among which MRPL36 showed the greatest prognostic significance." (PMID 33934540, 2021). "MRPL36 is a mitochondrial ribosomal protein that has not been studied in BRCA, but MRPL36 has been correlated with poor progression-free survival in ovarian cancer." (PMID 35707265, 2022).
oesophageal cancer (1 paper, 2018). "MRPL36 was not related to the prognosis of oesophageal cancer." (PMID 29343747, 2018).
cancer (3 papers, 2018 to 2024). A tumor composed of atypical neoplastic, often pleomorphic cells that invade other tissues. "Collectively, increased expression of MRPL36 has been linked to a wide variety of metastatic traits, thus further evidence of its importance in cancer metastasis across a broader range of cancer types would be of value." (PMID 39354291, 2024). "Among the top 10 DRGs identified for Korean (GSE24375), six genes are GC related (ESRRG, LIMS1, GATA3, GATA6, SOX9, POU2F1) and the other four are cancer related (IRF2, RGS3, MRPL36, FOSB)." (PMID 29745833, 2018).
MRPL36 also shares sentences with these, for which no sentence is quoted: lung carcinoma (1 paper); Salmonella Infections (1).